BRAF (B-Raf proto-oncogene, serine/threonine kinase)
Diseases named in the same sentence as BRAF in open-access papers (continued):
Sharing a sentence is not in itself a finding about the gene and the disease.
cancer (continued). "The BRAF mutation in canine cancers may also represent a molecular marker and therapeutic target in veterinary oncology." (PMID 29061943, 2015). "PRDM5 mutation was present in a small percentage of BRAF wild type cancers and this may be a cause of downregulation in this cancer subgroup." (PMID 25613750, 2015). "Coupled with the FISH analysis, the unique high incidence rates of BRAF mutation in canine PC and UC suggest that this mutation may serve as a potential cancer marker for these diagnostically challenging cancers." (PMID 29061943, 2015). "Among the three forms of RAF genes, BRAF gene is most frequently mutated in human cancer." (PMID 29061943, 2015). "Clinical studies showed that cancer patients with BRAF mutation have a relatively poor prognosis." (PMID 26168967, 2015). "Analysis of recent SNP array data, revealed loss over this locus in 33% BRAF mutant/MSS and 44% BRAF wild type cancers, which suggests gene deletion may also contribute to the levels of down-regulation observed." (PMID 25613750, 2015). "Thus, we interrogated MDP searching for drugs with selective cytotoxicity for cancer cells bearing BRAF mutations." (PMID 26513174, 2015). "Recently published retrospective, multicentre analyses, involving a large group of PTC patients have demonstrated the association between BRAF mutation and both cancer-related mortality and PTC recurrence, albeit partially depending on other disease risk factors." (PMID 26177218, 2015). "Interestingly, these variants are the third most common BRAF mutations in cancer (Cosmic Release v70), and often co-exist with RAS mutations, which otherwise generally occur in a mutually exclusive manner." (PMID 26090869, 2015). "Recently, several studies have demonstrated that a BRAF V600E mutation–specific monoclonal antibody (clone VE1) could detect the V600E mutated BRAF protein in different carcinomas." (PMID 25784606, 2015). "In addition, there were no significantly difference in aspects of pT stage, pN stage and disease stage among KRAS-mutated, BRAF-mutated and wild type carcinomas." (PMID 25929517, 2015). "Whereas, BRAF-mutated carcinomas more frequently demonstrated histologic features such as proximal location (60.9% vs 20.9%, p = 0.001), low-grade histology (43.5% vs 18.0%, p = 0.005), mucinous differentiation (69.6% vs 25.9%, p = 0.001) and deficient MMR (dMMR) (21.7% vs 7.6%, p = 0.03)." (PMID 25929517, 2015). "The BRAF V600 hotspot mutation occurs with a frequency of ~45% in melanoma and papillary thyroid cancer, and about ~10% in colorectal cancer, and the same mutation is typically observed in 0-4% of most other cancers." (PMID 25435088, 2014). "Targeting of the BRAF mutation leads to a loss of these hallmarks of cancer." (PMID 24885690, 2014). "For example PI3Kalpha, RAS, and BRaf mutations are well represented in cancer cell lines." (PMID 24904423, 2014). "In concordance with an earlier study we hypothesize that lack of a propensity for hypermethylation and other factors in Saudi CRC prevents the driver BRAF mutation in premalignant lesions to progress to full blown cancers." (PMID 25005754, 2014). "Targeting of mutant BRAF alleles leads to a loss of these hallmarks of cancer." (PMID 24885690, 2014). "The BRAF gene is the second most common gene mutated in human cancers." (PMID 25563358, 2014). "Over 45 cancer-associated mutations have been identified in BRAF." (PMID 25037456, 2014). "To examine this association, we modeled cancer cell variants with wild-type BRAF in silico." (PMID 24884660, 2014). "Interestingly, the presence of the BRAF V600E mutation in MSS cancers confers an even worse prognosis, however CIN has not been extensively studied on a genome-wide basis in this cancer subgroup." (PMID 24651849, 2014).
cancer (continued). "The relationship between borderline ovarian tumors and low-grade carcinomas has been investigated at the gene level by many groups focusing on the mutually exclusive mutations detected in either the BRAF or KRAS gene, and a relationship was found between the two groups of tumors." (PMID 24886194, 2014). "Germ line mutations in RAS or BRAF introduce distinct amino acid changes from those found in somatic cancer cells, and they can cause a spectrum of developmental defects such as cardio-facio-cutaneous (CFC) syndrome and Noonan or Costello syndrome, but do not appear to be overtly oncogenic." (PMID 23505473, 2013). "Examples are frequent somatic mutations of KRAS codons 12 and 13 in various types of cancers in endodermal organs (pancreas, colon, lung, etc.), and the prevalent mutation in the kinase domain of BRAF, BRAFV600E in cancer cells of endodermal (thyroid, colon) and ectodermal (melanoma) tissues." (PMID 23505473, 2013). "Furthermore, the carcinoma sections were positively tested for the BRAF V600E mutation using the ViennaLab BRAF Strip Assay (Vienna, Austria)." (PMID 23657056, 2013). "Taking everything into account, the main goal in cancer treatment is to increase patient survival, while the idea of whether BRAF mutation per se actually affects patient survival has been a matter of debate." (PMID 23056577, 2012). "In addition, it has been demonstrated that BRAF mutation is highly involved in main steps of cancer development and progression." (PMID 23056577, 2012). "They observed a strong relationship of CIMP cancers with BRAF mutations." (PMID 22792460, 2012). "While new drugs aimed at BRAF-mutated cancers are entering clinical practice, cells and tumors with activating Ras mutations are relatively resistant to those and quite a few other anti-cancer agents." (PMID 22869096, 2012). "The data presented here supports the hypothesis that a poorer prognosis may be driven by CIN at defined chromosomal locations in MSS cancers bearing a BRAF mutation." (PMID 23110075, 2012). "Whilst this is concordant with the diploid nature of BRAF mutant/MSI serrated pathway cancers with CIMP which progress via a high mutational rate, it does not explain how BRAF mutant/MSS serrated pathway cancers progress and especially the fact that their prognosis is particularly poor." (PMID 23110075, 2012). "The higher average fractional allelic loss (FAL) score observed for BRAF wild type versus mutant MSS cancers may reflect the earlier onset of CIN and therefore greater accumulation of CIN events." (PMID 23110075, 2012). "BRAF is one of the most frequently mutated protein kinase in cancer." (PMID 22039425, 2011). "An association between PIK3CA and RAS or BRAF mutations has implications for cancer therapy." (PMID 21829508, 2011). "BRAF mutations are found in many types of cancer, predominantly in up to 80% of melanoma and nevi." (PMID 21943394, 2011). "In addition to the two novel BRAF mutations identified, two additional mutations which have been previously reported in cancer were identified." (PMID 18060073, 2007). "Although the study of BRAF and its transcript variants in this cancer type is still in its infancy, we propose that the BRAF‐204 transcript might sustain not only the ERK pathway but also the PI3K/AKT pathway by sponging the oncosuppressive miR‐423 and relieving its targeting of PDPK1." (PMID 40415485, 2025). "Additionally, patients aged 65 and older with squamous CC show a higher frequency of PIK3CA mutations, which are associated with increased mutation rates in other genes involved in key cancer-associated pathways, such as tyrosine kinase receptors, K-Ras/BRAF/MAPK and the Wnt/β-catenin pathway." (PMID 40003544, 2025). "Therefore, UA might cause the suppression of cancer cell proliferation by inhibiting the expression of the BRAF gene carrying the BRAF-V600E mutation and by upregulating caspase genes, which are the processors of apoptosis." (PMID 39473730, 2024).
cancer (continued). "Additionally, 10 studies explored the association between BRAF mutations and cancer histology." (PMID 38394545, 2024). "Previous work suggests that the BRAF mutation tends to have a different functional signature in THCA than other cancer types, and withholding THCA from the training set improved classifier performance, which could at least in part explain the difficulty of generalizing to THCA we observe." (PMID 39776849, 2024). "Indeed, this result reinforces the concept of BRAFV600E PMP cancer as very addicted to BRAF mutation and suggests that encorafenib monotherapy could be a great promise for patients with mutated PMP." (PMID 39018564, 2024). "Thus, the desire for a non-invasive means of diagnosing these cancers led to the finding that the BRAF p.V595E mutation could be detected from neoplastic cells or cell-free DNA (cfDNA) in the urine of dogs with UC." (PMID 38787171, 2024). "However, BRAF mutations are rarely observed in other types of human cancers." (PMID 39052013, 2024). "Furthermore, despite not meeting the threshold for statistical power defined by this study, there is an observable trend that only malignant Bethesda III nodules demonstrated BRAF V600E (n = 4) (p = 0.053) mutations on molecular testing, three of which led to aggressive cancer." (PMID 39766147, 2024). "Thus, the identification of BRAF mutations from FFPE biopsy material could provide a valuable opportunity to enhance routine cancer treatment strategies not only in human medicine but in veterinary oncology as well." (PMID 39591358, 2024). "Accordingly, the HMH genomic DNA mixture was determined to carry 24.1% KRAS c.35G > T, 10.1% BRAF c.1391G > T, and 24.1% BRAF c.1799T > A. The values are consistent with the theoretical value calculated from the gene mutation genotypes of the three cancer cell lines." (PMID 37686219, 2023). "The genetic and biochemical heterogeneity of this aggressive cancer with high metastatic potential and limited response to chemotherapeutic agents is associated, among other occurrences, with high frequency of mutations such as those in the BRAF, NRAS, and C-KIT genes." (PMID 36674631, 2023). "Furthermore, while BRAF mutations are reported in only 1.4% of human urinary tract cancers, the V600E variant constitutes 95.9% of amino acid substitutions found within this gene across all human cancers." (PMID 37079639, 2023). "Thirdly, clinical markers that may affect bone metastasis of cancer, including BRAF mutation, calcitonin, TERT mutation, and Ki-67 index, were not included in this study, and we will continue to expand our data collection to further improve our model in the future." (PMID 36950687, 2023). "In addition, non-V600 BRAF variants have been identified in many types of cancer." (PMID 36867406, 2023). "Thus, concomitant PIK3CA mutations could provide the required WNT/β-catenin pathway activation in BRAF mutated cancers." (PMID 36079062, 2022). "However, the role of BRAF inhibitors in non-BRAF mutated cancers is reported to be controversial." (PMID 36387901, 2022). "Co is associated with thyroid cancer, and inhibition of MEK1/2 kinase activity by Co chelating agents may be used in combination with other MAPK pathway inhibitors to treat BRAF mutation-positive cancers and cancers resistant to BRAFV600E and MEK1/2 inhibitors." (PMID 36353227, 2022). "Thus, these mutations may play a role in resistance of a subset of BRAF mutated cancers to targeted therapies, through the extensive crosstalk of the KRAS/RAF/MEK/ERK and the PI3K/AKT/mTOR pathways." (PMID 36079062, 2022). "In addition, survival analysis between BRAF expression and patient relapse-free survival (RFS) across various cancer types exhibited that increased BRAF expression was associated with poor RFS in LIHC, LUSC, and UCEC, while high BRAF expression was correlated with better RFS in BRCA and OV." (PMID 35910024, 2022). "Other types of cancer may harbor BRAF mutations or MAPK pathway aberrations." (PMID 36254250, 2022).
cancer (continued). "However, as the cancer with the same potential for KRAS/BRAF mutations, the function of AHCYL1 continues to be unknown in CRC." (PMID 35578598, 2022). "Notably, an increasing number of research studies have indicated that SHP2 inhibitors show efficacy in subsets of RTK-, KRAS-, and BRAF-driven cancers, although it has been previously reported that cancer cells carrying oncogenic RAS/RAF mutations would be refractory to SHP2 inhibition." (PMID 35462913, 2022). "Although it is self-evident that histopathology and BRAF mutation testing identify different features of a disease, i.e., the morphological and molecular features, similarly it is self-evident that the latter may support the histopathological diagnosis whenever a carcinoma carries the BRAF variant." (PMID 35711804, 2022). "Besides cancers with prevalent oncogenic mutations (e.g., BRAF mutation in melanoma, c-kit or PDGFR mutations in gastrointestinal stromal tumors), BTCs are now known to present one of the highest frequencies of targetable molecular alterations across cancer types." (PMID 33805461, 2021). "Therefore, targeting PLCB1 and DESC1 could be potential strategies for inhibiting the resistance to MEK1/2 inhibition in certain cancers with NRAS or BRAF mutations." (PMID 34064422, 2021). "In addition, patients with both cancers have a high frequency of BRAF V600E mutation." (PMID 33578751, 2021). "Results of this study suggest a need to revisit the classification of BRAF alterations, which has important clinical implications because personalized treatment strategies could be developed for RAS-dependent BRAF variant cancers based on different mechanisms of RAS activation." (PMID 33507258, 2021). "For example, by observing the SPNs of mutated BRAF, we noticed that inhibiting the six sensitive SPs or activating the four resistant SPs could be therapeutic strategies for precisely treating BRAF-mutated cancer." (PMID 34681774, 2021). "Therefore, anti-VEGF therapies are recommended for BRAF mutated cancer patients." (PMID 34381786, 2021). "Our data suggest that PD-L1 might represent a useful prognostic marker in Middle Eastern PTC and PD-L1 inhibition could be a potential therapeutic option for aggressive PTC cancers, such as the tall cell variant, BRAF mutation-positive patients that are unresponsive to standard treatment." (PMID 33535609, 2021). "Interestingly the two PTCs harboring both the TERT and BRAF mutations have a very different prognosis suggesting that the different germline mutational status may play a role in the modulation of cancer aggressiveness." (PMID 33821390, 2021). "In addition, gene mutations, such as PIK3CA and BRAF, may also have an impact on the benefits of aspirin use for several types of cancer." (PMID 32545461, 2020). "In view of these evidences, we hypothesized that the proto-oncogene BRAF is activated by mutations promoting the phosphorylation of its activation loop, implying the feasibility of applying PTMsnp to analyze cancer mutations from the perspective of affecting PTM modification." (PMID 33240890, 2020). "However, it has to be noted that although both AMPK inhibitors and activators may synergistically enhance the therapeutic efficacy of RAF inhibitors against BRAF-mutated cancers, molecular mechanisms underlying these phenomena are completely different." (PMID 32807225, 2020). "Finally, BRAF mutated cells also have angiogenic capacity, since they can induce other cancer cells and microenvironmental cells to secrete CXCL8 and CCL2, two pro-tumorigenic chemokines, leading to cancer cell proliferation and macrophage-mediated angiogenesis." (PMID 33193402, 2020). "Similarly, RAF mutations have isoform preference in cancers as Ras mutations with BRAF >> CRAF > ARAF, which may arise from their different basal activities." (PMID 32807225, 2020).
cancer (continued). "Moreover, an FDA-approved combination of dabrafenib and trametinib administered in a molar ratio of 1:80 is routinely used for treatment of BRAF-mutated cancers as it is demonstrated to effectively enhance the inhibition of the BRAF pathway and increase survival of patients." (PMID 33268358, 2020). "Thus, this basket trial established a standard of care for these rare cancers with BRAF mutation." (PMID 31032221, 2019). "Thus reversibility of MEKi-resistance and the consequences of MEKi withdrawal may be influenced by the nature of the particular amplified oncogene - BRAF or KRAS - highlighting again the challenges of targeting cancers with KRAS mutations." (PMID 35582726, 2019). "It will be important to examine if N-terminally truncated BRAF, as detected in several human cancers, is linked with phosphorylated MEK nuclear accumulation and whether this is associated with any of the key biochemical and cellular characteristics previously linked with aberrant MEK localisation." (PMID 30603699, 2018). "Reduced levels of CDX2 staining which is correlated with MSI, BRAF mutation, and CIMP were also found in the BRAF mutant/MSS cancers, which suggests that epigenetic silencing associated with CIMP and the BRAF mutation may be contributing to downregulation of CDX2." (PMID 30598662, 2018). "However, therapeutic efficacies are low in most cancers with KRAS or BRAF mutations." (PMID 28002807, 2017). "Therefore, it has yet to be determined whether over time activated CRAF can contribute to kinase-independent resistance mechanisms to RAF inhibitors in BRAF mutated cancers." (PMID 28947956, 2017). "By shedding light on the repertoire of BRAF mRNA and protein variants, and on the complex regulation of their expression, our work paves the way to a deeper understanding of a crucially important player in human cancer and to a more informed development of new therapeutic strategies." (PMID 28454577, 2017). "However, it remains unclear why the valine-to-glutamate mutation is so much more common in cancer cells than any other mutation that could affect the pocket in BRAF." (PMID 26744778, 2016). "However, all mutations were present in BRAF wild type cancers which may still indicate this mechanism is of some relevance in traditional pathway cancers." (PMID 25613750, 2015). "The relatively low number of patients with cancer relapse in our cohort precludes any definitive conclusions, although we observe a slight and insignificant trend towards the increased relapse rate when BRAF mutation is considered with reference to LN metastases and extrathyroidal invasion." (PMID 26177218, 2015). "Furthermore, there was an association of PRDM5 methylation being more prevalent in BRAF mutant cancers presenting at late compared to early stages which further indicates epigenetic regulation of PRDM5 may influence disease progression in the serrated pathway." (PMID 25613750, 2015). "Also, this explains why a cancer mutation might often be embryonic lethal, as shown for the BRAF V600E mutation." (PMID 24803665, 2014). "Notably our results suggest the possibility that the correlation between RAS and BRAF mutations and the response to antifolate drugs might be relevant in other cancer types although further efforts to confirm this hypothesis are warranted." (PMID 24941944, 2014). "Importantly, our findings suggest that the correlation between NRAS and BRAF mutations and their differential response to antifolate drugs might apply to other cancer types." (PMID 24941944, 2014).